EGFR (epidermal growth factor receptor)
Diseases named in the same sentence as EGFR in open-access papers (continued):
Sharing a sentence is not in itself a finding about the gene and the disease.
radiation pneumonitis (14 papers, 2020 to 2025). Inflammation of the lung due to harmful effects of ionizing or non-ionizing radiation. "Another retrospective study compared the incidence of grade 2 and above radiation pneumonia in first-generation EGFR-TKI (Gefitinib, Erlotinib, and Icotinib) synchronous chest radiotherapy." (PMID 38115908, 2023). "The final multivariate model incorporated sex, smoking history, histology (including EGFR mutation status), TNM stage, planning target volume, chemotherapy sequence and radiation pneumonitis grade." (PMID 34927371, 2022). "A phase II study of upfront concurrent EGFR-TKI and thoracic radiotherapy for Stage IV EGFR-mutated NSCLC reported a grade 3+ radiation pneumonitis rate of 20%." (PMID 36010982, 2022). "Several studies have shown a potential value of concurrent epidermal growth factor receptor-tyrosine kinase inhibitor (EGFR-TKI) with thoracic radiotherapy in EGFR-mutated population, but a high risk of radiation pneumonitis raised a major concern." (PMID 33962566, 2021). "It was found that although the incidence of ≥ grade 2 radiation pneumonia was higher than that of synchronous radiotherapy and chemotherapy, the use of Icotinib, ipsilateral lung V30 ≤ 34%, or EGFR-TKI overlapping with chest radiotherapy for ≤ 20 days can be reduced." (PMID 38115908, 2023). "However, previous studies have showed that EGFR-TKI combined with radiotherapy can also increase the incidence of radiation pneumonitis." (PMID 33962566, 2021). "RECEL study also showed grade ≥ 3 radiation pneumonitis was 16.7% in the EGFR-TKI concurrent group." (PMID 33962566, 2021). "Recent studies have shown that for patients receiving both EGFR-TKI and radiotherapy, overlapping treatment duration is an independent risk factor for radiation pneumonitis, suggesting that reducing overlap time can decrease the incidence of radiation pneumonitis." (PMID 40071087, 2025). "Severe radiation pneumonitis might counteract the benefit of EGFR-TKI and radiotherapy." (PMID 33962566, 2021). "The exact rate and relevant risk factors of radiation pneumonitis (RP) for non-small-cell cancer (NSCLC) patients treated with the combination of epidermal growth factor receptor-tyrosine kinase inhibitors (EGFR-TKIs) and thoracic radiotherapy have not been reported." (PMID 33622352, 2021). "For first-generation and third-generation (Osimertinib, aumolertinib) EGFR-TKIs combined with TRT, the incidence of radiation pneumonitis was 33%, 63.6%, and 42.9%, respectively." (PMID 40071087, 2025). "Therefore, it was suggested that the best time to strengthen the local control and reduce the incidence of radiation pneumonia might be the treatment with a thoracic radiotherapy scheme of more than 60 Gy after taking EGFR TKI drugs until the tumor volume is stabilized during follow-up." (PMID 36153486, 2022). "This study aims to explore the safety of concurrent radiotherapy with almonertinib in EGFR-mutant local advanced NSCLC patients, most importantly the incidence of radiation pneumonitis." (PMID 33962566, 2021). "In another retrospective study, among 45 unresectable stage III NSCLC patients receiving radiotherapy with EGFR-TKI, 17 patients (37.7%) suffered radiation pneumonitis, but achieved satisfactory PFS and OS: 27.9 (95% CI: 18.7–37.2) and 49.7 (95% CI: 27.7–71.8) months." (PMID 34322390, 2021).
serous ovarian cancer (14 papers, 2008 to 2025). "This study indicates that with regard to EGFR and cytoplasmic galectin-3 immunoexpression, multiple marker testing may be an adjunct in the identification of high-risk ovarian serous cancers." (PMID 23658855, 2010). "Interaction between ALDH1 and EGFR in high-grade serous ovarian cancer positive for both molecules correlated with poor survival." (PMID 30002682, 2018). "The effect of BRCA1 on EGFR was assessed in 146 serous ovarian cancer patients (28 pairs of BRCA1-mutated or not, 23 pairs of BRCA2-mutated or not, and 22 pairs with hypermethylated BRCA1 promoter or not)." (PMID 24321281, 2013). "EGFR activation can drive HIF-1α up-regulation, leading to VEGF gene expression and providing a positive feedback loop in high grade serous ovarian cancer." (PMID 38057816, 2023). "Significantly high levels of MYC, EGFR, and CCND1 were detected in platinum-resistant high-grade serous ovarian cancer cell lines." (PMID 35739532, 2022). "GEO-based analysis of microarray GSE189717 showed ectopic expression of MYC, EGFR, and CCND1 in platinum-resistant high-grade serous ovarian cancer cell lines." (PMID 35739532, 2022). "To further validate the relevance of MYC, EGFR, and CCND1 to platinum chemotherapy response, we analyzed their differential expression between platinum-sensitive and platinum-resistant high-grade serous ovarian cancer cells based on GEO microarray (GSE189717)." (PMID 35739532, 2022). "In high‐grade serous ovarian cancer (HGSOC), combination of MEK (AZD6244) and SRC (saracatinib) inhibitors overcomes EGFR‐mediated bypass of the RAS‐MAPK pathway and targets tumour initiating stem cells." (PMID 34856074, 2022). "Checkpoint kinase 1 (Chk1) and epidermal growth factor receptor (EGFR) are therapeutic targets for treatment of acute and chronic leukemias and high-grade serous ovarian cancer." (PMID 34067242, 2021). "Since EGFR and FGFR stimulate a similar repertoire of intracellular signaling pathways, this certain pattern of expression evident in the recurrent serous ovarian cancers deserves special consideration." (PMID 18211683, 2008).
synovial sarcoma (14 papers, 2006 to 2025). "In addition, epidermal growth factor receptor (EGFR) has been reported to be overexpressed in synovial sarcoma compared to other soft tissue cancers, and high EGFR expression has been associated with poor prognosis." (PMID 38681356, 2024). "Such an EGFR-specific treatment option was performed in a phase II trial for patients with synovial sarcomas and could be considered for other mesenchymal tumors that express HIF-1α." (PMID 30513863, 2018). "In a synovial sarcoma study, only two of 13 tissue samples were positive for EGFR TK mutation, with no EGFR amplification on FISH analysis and a further study on EGFR gene amplification from patients with endometrial stromal sarcoma also showed 10/10 negative results." (PMID 28556791, 2017). "In a synovial sarcoma study, only 2 of 13 tissue samples were positive for EGFR TK mutation, with no EGFR amplification on FISH analysis and a further study on EGFR gene amplification from patients with endometrial stromal sarcoma also showed 10/10 negative results." (PMID 26909593, 2016). "None of the synovial sarcomas in our series demonstrated genomic amplification of EGFR, consistent with previous work." (PMID 25906748, 2015). "In fact, a prior clinical trial of gefitinib in synovial sarcomas with enrollment limited to patients overexpressing EGFR by IHC was without responses to this agent." (PMID 25906748, 2015). "Additionally, many other genes that have been previously related to synovial sarcomas, such as the SSX4 gene, EGFR and SALL2, components of the retinoic acid pathway (CRABP1 and RARG) as well as retinoic acid induced genes (IRX5 and TGFβ2), were also included in this module." (PMID 16503973, 2006).
ulcer (14 papers, 2013 to 2026). "For molecularly targeted agents such as anti-epidermal growth factor receptor drugs and angiogenesis inhibitors, the association with ulcers has been discussed in several studies." (PMID 39204191, 2024). "They claimed that EGF's interaction with its cell surface receptor (EGFR) has a big role in ulcer healing." (PMID 38652367, 2024). "Numerous experimental and epidemiological investigations supplied strong evidences that EGF/EGFR signaling pathway played a pivotal role in ulcer repair." (PMID 23825635, 2013). "According to one hypothesis, the inhibition of squamous epithelial maturation by anti-epidermal growth factor receptor agents contributes to ulcer development." (PMID 39204191, 2024). "EGF and EGFR could inhibit the secretion of gastric acid, and their autocrine system plays an important role in cell proliferation and differentiation during ulcer healing." (PMID 26978395, 2016). "Compared with the oral ulcer + saline group, the nicotine-treated group showed greater epithelial thickness, lower fibrosis, lower MDA and TNF-α levels, and higher VEGF-A and EGFR levels at the study endpoint." (PMID 42195153, 2026). "Furthermore, EGF is the ligand of EGFR, which is secreted in the gastrointestinal tract and could facilitate epithelial cell repair, reduce gastric acid secretion and promote the healing of ulcers." (PMID 32276345, 2020). "As regards cell renewal, previous studies verified the involvement of epidermal growth factor receptor (EGFR) signaling in the proliferation and differentiation of gastric epithelial cells, as well as in gastric injury repair and ulcer healing." (PMID 29523851, 2018).
Allergy (13 papers, 2016 to 2025). An allergy is an immune response or reaction to substances that are usually not harmful. "DUOX1‐dependent phosphorylation of Src and EGFR in mice exposed to Alternaria extract demonstrates a similar role for DUOX1 in fungal‐induced allergy." (PMID 37357550, 2023). "The metabolization of L-tyrosine by bacteria in the gut increases the concentration of p-cresol sulfate (PCS), which has been shown to be protective against HDM-induced allergy by interfering with epidermal growth factor receptor (EGFR) and TLR4 signaling." (PMID 34012456, 2021). "In the present study, ADRs that were different from those previously reported for EGFR-TKIs were found, such as allergy-like dermatological toxicity, pyrexia, platelet count decreased, and embolic and thrombotic events." (PMID 30790152, 2019). "A systematic review was conducted to identify observational studies or clinical trials of mCRC patients treated with anti‐EGFR therapies that reported occurrences of IRs, hypersensitivity, or allergy/anaphylaxis." (PMID 31376243, 2019). "While allergy-like dermatological toxicities (e.g., urticaria) were observed in the present study, acneiform eruption has been reported with conventional EGFR-TKIs." (PMID 30790152, 2019). "EGFR signaling plays a complex role in the inflammatory response of epithelial surfaces such as skin and mucosa to injury, allergy and infection." (PMID 27414801, 2016).
Arrhythmia (13 papers, 2020 to 2026). Any cardiac rhythm other than the normal sinus rhythm. "Osimertinib therapy is associated with an increased risk of HF and a decline in LVEF compared to other EGFR inhibitors, while associations with MI and arrhythmias were less consistent." (PMID 41801573, 2026). "The primary PT in arrhythmia is tachycardia, with several case reports pointing to EGFR-TKI-associated ventricular tachycardia." (PMID 38664423, 2024). "With the prevalence of EGFR mutations in Asian populations, the risk of arrhythmia among patients with NSCLC remains unclear." (PMID 37139162, 2023).
cardiomyopathy (13 papers, 2010 to 2025). A disease of the heart muscle or myocardium proper. "The EGFR signaling pathway is participated in biological activities like cycle regulation, division, and cell proliferation and is closely associated with the development of cardiovascular diseases such as cardiomyopathy and cardiovascular injury." (PMID 36046382, 2022). "To further validate the effect of EGFR inhibitors against hyperlipidemia-induced cardiomyopathy, we performed similar experiment in C57BL/6 WT mice." (PMID 27087279, 2016). "We found that especially miRNAs contained within EVs may be informative in terms of cardiomyopathy development and may regulate pathways related to neurotrophin signaling, transforming growth factor beta (TGFβ) or epidermal growth factor receptors (ErbB)." (PMID 36517751, 2022). "A new series of imidazothiazole derivatives bearing thiazolidinone moiety (4a-g and 5a-d) were designed, synthesized and evaluated for potential epidermal growth factor receptor (EGFR) kinase inhibition, anticancer and anti-inflammatory activity, cardiomyopathy toxicity and hepatotoxicity." (PMID 38605072, 2024). "The patient was subsequently started on afatinib, a second-generation epidermal growth factor receptor-tyrosine kinase inhibitor (EGFR-TKI), without recurrence of cardiomyopathy." (PMID 37908018, 2023).
gastric ulcer (13 papers, 2009 to 2025). An ulcerated lesion in the mucosal surface of the stomach. "EGFR is important for the proliferation and differentiation of gastric mucosal cells, and its expression increases during early stages of gastric ulcer healing." (PMID 36292949, 2022). "Nonetheless, previous studies described that the increased expression of EGFR in the epithelial cells of gastric ulcer margins is essential for improving to take place." (PMID 32549798, 2020). "It is evident that ZJW can upregulate the expression level of EGFR in rats with gastric ulcer induced by acetic acid, promoting the restoration of damaged gastric mucosa." (PMID 30382864, 2018). "Moreover, TCM treatment can decrease the expression of EGFR in gastric mucosal tissue from gastric ulcer patients diagnosed with DLS or syndrome of liver invading the spleen." (PMID 24454509, 2013). "Indeed, it was recently shown that gastric ulcer healing in rats is promoted by cathelicidin-mediated transactivation of epidermal growth factor receptors (EGFR) via the transforming growth factor alpha (TGFα) signaling pathway." (PMID 19728885, 2009). "The expression of markers of proliferation (KI67 and EGFR) and angiogenesis (factor VIII and CD31) decreased significantly (p < 0.05) in older rats when compared with younger ones (3 months > six months > 12 months > 18 months) on days 7, 14, and 21 after induction of gastric ulcer." (PMID 32549798, 2020). "Also, increased phosphorylation of EGFR resulted in an upsurge of MAP-ERK-1 and ERK-2 kinase phosphorylation levels and actions with more than 440% and 880% folds, respectively, at the initial phases of the healing of an experimental gastric ulcer accelerated healing." (PMID 32549798, 2020).
mucinous adenocarcinoma (13 papers, 2014 to 2025). An invasive adenocarcinoma composed of malignant glandular cells which contain intracytoplasmic mucin. "Moreover, TTF-1-negative and HNF4α-positive non-mucinous adenocarcinomas showed wild-type EGFR and frequent SMARCA4 loss, and tended to show a high-grade solid morphology and very poor prognosis." (PMID 38710944, 2025). "Major rationales for changes in adenocarcinoma histologic variants are that the invasive mucinous type shows frequent mutations in KRAS and hardly any in EGFR, whereas non-mucinous adenocarcinoma of predominant lepidic subtype is characterized by frequent mutations in EGFR and fewer in KRAS." (PMID 24879454, 2014). "Patients with mucinous adenocarcinoma responded statistically significantly worse to anti-EGFR therapy (p = 0.001) (mucinous 16.7%: NOS, Singnet ring c." (PMID 39202071, 2024). "We found that 3.0 and 4.0% of the 594 CRC patients (63.6% of COAD, 26.1% of READ and 10.3% of mucinous adenocarcinoma (MUAD)) in the dataset respectively harbored genetically altered EGFR and c-MET." (PMID 34512327, 2021). "Another study also reported upregulated expression of FSCN1, cortactin, and EGFR in TMAs of four ovarian carcinomas (serous carcinoma, mucinous carcinoma, endometrioid adenocarcinoma, and clear cell carcinoma)." (PMID 34830909, 2021). "The strongest correlation between a histological subtype and a set of molecular and biologic features is that of invasive mucinous adenocarcinomas, which typically have KRAS mutations and lack EGFR mutations." (PMID 29065153, 2017). "All cases of mucinous, enteric, and colloid adenocarcinoma were HNF4α-positive, TTF-1-negative, and SMARCA4 retained, and showed a high frequency of KRAS mutations (10/18, 55.6%) and no EGFR mutations (0/18, 0%)." (PMID 38710944, 2025). "These subtypes are mostly represented by invasive mucinous adenocarcinoma representing roughly 10% of lung tumors and are often EGFR wild type and TTF-1 negative." (PMID 35885495, 2022). "Our results indicated that L-PLADC showed a strong tendency for acinar-predominant subtype and EGFR positive mutations, whereas D-PLADC was closely related to invasive mucinous adenocarcinoma and EGFR negative mutations." (PMID 34787725, 2021). "Invasive mucinous adenocarcinoma (mucinous bronchioloalveolar carcinoma) has been known to correlate with KRAS mutation and harbor no EGFR mutation." (PMID 26318038, 2015).
mucoepidermoid carcinoma (13 papers, 2008 to 2024). A carcinoma morphologically characterized the presence of cuboidal mucous cells, goblet-like mucous cells, squamoid cells, cystic changes, and a fibrotic stromal formation. "Recently, we identified a mucoepidermoid carcinoma and an ACC with a TKI-sensitising EGFR exon 19 deletion mutation by screening EGFR exons 19 and 21 for the two most common hotspot mutations by an allele-specific PCR test." (PMID 19174819, 2009). "AREG secreted by mucoepidermoid carcinoma (MEC) cells may activate EGFR Tyr1068 in an autocrine manner, suggesting potential therapeutic applications for MEC." (PMID 39451251, 2024). "The epidermal growth factor receptor protein is overexpressed in approximately 70% of mucoepidermoid carcinoma patients and may represent a therapeutic target." (PMID 18826647, 2008). "However, it will be important to investigate, whether the respective fusion proteins depend in a similar way on unmutated EGFR signaling for their tumorigenic function as does the CRTC1-MAML2 fusion protein in EGFR inhibitor-sensitive mucoepidermoid carcinomas." (PMID 33674910, 2021). "Recently we identified a relationship between human cytomegalovirus (hCMV) and human salivary gland (SG) mucoepidermoid carcinoma (MEC) in over 90% of cases; tumorigenesis in these cases uniformly correlated with active hCMV protein expression and an upregulation of the EGFR → ERK pathway." (PMID 23342981, 2013). "However, partial response to trastuzumab was reported for a mucoepidermoid carcinoma with HER2 3+ immunostaining and prolonged tumour progression to lapatinib was documented in three non-ACC tumours with HER2 amplification and 3+ staining for EGFR and HER2." (PMID 22240798, 2012).